INS (insulin)
Diseases named in the same sentence as INS in open-access papers (continued):
Sharing a sentence is not in itself a finding about the gene and the disease.
diabetes (continued). "Since it was identified that TNF-α secretion by adipocytes played a role in the body's update of glucose and response to insulin which contributes to the development of diabetes, extensive research has been done looking at the role of inflammation in diabetes." (PMID 30534081, 2018). "Among patients with type 2 diabetes mellitus, the need for intake of insulin for glycemic control did not modify the risk for death in the case of IAIs (OR: 1.21; 95%CIs: 0.58–2.51; p: 0.607)." (PMID 29843641, 2018). "Furthermore, steroid-induced diabetes-like hyperglycemia was generated in mice by prednisolone administration, which is known to inhibit the action of insulin and stimulate hepatic gluconeogenesis." (PMID 29933567, 2018). "We found that diabetes distress but not depression was associated with insulin use after adjustment for other potential confounders." (PMID 29777153, 2018). "Overall, our results indicate the need to implement integrated diabetes care programs specifically tailored to the needs, values and preferences of younger patients and to those on insulin therapy, with longer disease duration and/or higher HbA1c levels and older patients with high SBP levels." (PMID 29405097, 2018). "Excessive systemic iron can cause oxidative stress injury in hepatocytes and pancreatic β cells, forming the basis of diabetes, which may lead to insulin resistance, reduction in insulin secretion, and eventually, development of T2DM." (PMID 29636044, 2018). "It has been proposed that early exposure to hyperglycemia and elevated insulin levels may lead to malprogramming of the fetus leading to the subsequent development of diabetes and obesity." (PMID 29470513, 2018). "The secondary purpose was to begin examining the Diabetes Injection Device Preference Questionnaire (DID-PQ) in the subgroup of patients who had been treated with multiple non-insulin injection devices and were therefore able to report preferences between two devices." (PMID 30294714, 2018). "Homeostasis model assessment estimates insulin resistance (HOMA-IR) from fasting levels of insulin and glucose; other measures that have been used to identify insulin resistance or diabetes include fasting insulin and glycosylated hemoglobin (HbA1c), respectively." (PMID 30266080, 2018). "Insulin therapy is a recommended therapy to treat diabetes mellitus despite its side effects." (PMID 30347680, 2018). "Overall, our results sugget that the human IR meta-signature might be utilized as a pre-screening tool for developing diabetes treatments or insulin-sensitizing drugs." (PMID 29487289, 2018). "In a multivariable log-binomial regression, the mean postprandial glucose was significantly associated with GDM recurrence (p = 0.017) after adjusting for maternal age, family history of diabetes, insulin use, and inter-pregnancy interval (PR = 1.04 [95% CI: 1.01, 1.07])." (PMID 29679039, 2018). "Sensor accuracy was unaffected by the type of diabetes, the stage of pregnancy, whether insulin was used, age or body mass index." (PMID 29470094, 2018). "Together these findings suggest that the increased diabetes risk in OSA is associated with increased insulin resistance without adequate compensation by the beta-cell." (PMID 30042734, 2018). "Furthermore, Cr supplements have been reported to improve glucose intolerance in patients with diabetes, and influence carbohydrate and lipid metabolism by interacting with insulin." (PMID 29617349, 2018). "First, because we started and maintained good glycemic control from a very early stage of diabetes, diabetic complications may have been prevented or delayed in the insulin-treated rats during our study period." (PMID 29682576, 2018). "Diabetes is associated with progression to decreased insulin production with/without impaired insulin receptor function, leading to higher blood glucose levels." (PMID 30521580, 2018).
diabetes (continued). "Abnormalities in temporal patterns of insulin secretion and the consequent abnormal concentrations of circulating insulin contribute to the pathogenesis of type 2 diabetes mellitus, indicating that the metabolic response to insulin depends on its temporal patterns." (PMID 30267682, 2018). "Histopathological examination indicated that STZ treatment destroyed pancreatic islets and thus resulted in pancreatic beta-cells insulin secretion and beta-cell mass reduction significantly and led to diabetes (type 1 reduced 70% nearly and type 2 reduced 50% nearly)." (PMID 29853958, 2018). "The primary outcome of this prospective, blinded, single center, randomized controlled trial is to determine whether a diabetes-specific formula reduces exogenous insulin administration." (PMID 29631990, 2018). "We hypothesized that tumors of patients with diabetes mellitus have higher expression of proteins in the insulin signaling pathway, especially among those treated with insulin and/or insulin analogues." (PMID 29486734, 2018). "In addition, since it is a condition related to type 2 diabetes mellitus, and to insulin resistance, there is evidence that retinol can increase insulin sensitivity by promoting its increased signaling." (PMID 29385682, 2018). "After treatment of thiamine, diabetes was controlled and insulin was discontinued." (PMID 29379566, 2018). "Moreover, central injection of insulin has been reported to reinstate normal LH secretion in an experimental rat model of diabetes." (PMID 29643834, 2018). "In addition, the adherence to healthy diets is plausibly linked to healthier lifestyle-related habits and factors—such as obesity, smoking, physical activity, and education exposure—which influence insulin sensitivity and diabetes incidence." (PMID 29762478, 2018). "The American College of Sports Medicine, the American Heart Association and the American Diabetes Association recommend that adults perform at least 150–300 min/wk (21.4–42.8 min/day) of MVPA to maintain and promote cardiovascular health and insulin sensitivity." (PMID 30453553, 2018). "Diabetes in children is caused by lack of insulin, hence lifelong daily insulin therapy is an integral component among other treatment modalities in the management of childhood diabetes." (PMID 29986694, 2018). "However, on the contrary, an observational study (673 males and 849 females, Caucasian adults, all free of diabetes) found that age-adjusted fasting insulin levels were higher in males." (PMID 30211231, 2018). "Dysfunctional insulin secretion is a key factor to diabetes development in insulin-resistant individuals, and a plausible explanation to the very high prevalence of prediabetes and type 2 diabetes in individuals with a strong family history, that to 95% are represented by Iraqi immigrants." (PMID 29274011, 2018). "The beneficial effects of fiber-rich food in diabetes patients may be attributed to slow release of the absorbed glucose into the blood circulation resulting in decreased insulin secretion." (PMID 29527102, 2018). "One of the main functions of the pancreas is insulin secretion, which is altered in diabetes." (PMID 30013597, 2018). "Diabetes is often caused by β-cell dysfunction and recent studies have shown that SIRT6 may be important in glucose stimulated insulin secretion from these pancreatic β cells and SIRT6 may help improve insulin secretion in diabetics." (PMID 29966233, 2018). "Therefore, if we consider pre-diabetes a specific clinical condition for cognitive injury, physical exercise can promote benefits in insulin regulation and sensitivity." (PMID 29988330, 2018). "Similarly to AD, reductions in insulin sensitivity (i.e., insulin resistance) occur years before the patients start to experience the symptoms and are diagnosed with diabetes." (PMID 29743868, 2018).
diabetes (continued). "Our data show that in a population still free from diabetes familial burden influences insulin secretion to a higher degree than insulin action and may be a logical target for intervention." (PMID 29274011, 2018). "Accumulating evidence suggests that islet amyloid deposits may play a significant role in the progressive reduction in the number of insulin-producing cells and in the deterioration of islet function that occurs in diabetes." (PMID 29682407, 2018). "WS is characterized by insulin-requiring diabetes mellitus and optic atrophy." (PMID 29850290, 2018). "However, these mice are protected from streptozotocin-induced diabetes and display enhanced peripheral insulin sensitivity, as indicated by measurement glucose uptake and insulin-dependent glucose disposal." (PMID 30002646, 2018). "However, in the pre-diabetes period in GK rats (the first 3 weeks after birth), the whole body insulin sensitivity significantly increased when compared to the control Wistar rats." (PMID 30687391, 2018). "Therefore, differences in insulin signalling cannot fully explain the differences in autophagy when comparing the different types of diabetes." (PMID 30443826, 2018). "Over the last twenty years of research, vanadium compounds have been shown to act in a similar way to insulin on selected diabetes and metabolic syndrome models, in tests both on animals and humans as far as physiological symptoms and biochemical parameters are concerned." (PMID 30026756, 2018). "A prospective study with historical controls was conducted to evaluate the impact of a pocket insulin dosing guide on the diabetes management practices of internal medicine resident physicians at the Southern Illinois University (SIU) School of Medicine, rotating on general medicine." (PMID 30155381, 2018). "In order to determine whether Isx9 can improve β cell function and glycemia in vivo, we used a streptozotocin (STZ)-induced diabetic mouse model characterized by an ablation of the murine islet β cells; these mice become insulin-dependent and develop diabetes." (PMID 30150605, 2018). "In a diabetes study, researchers determined that endogenous and exogenous melatonin may influence metabolic disturbances not only by regulating insulin secretion but also by providing protection against ROS." (PMID 30174783, 2018). "The introduction of insulin analogs in the last decades had a great impact in the area of diabetes." (PMID 29615978, 2018). "Aggressive diabetes management in patients with ketosis-prone diabetes significantly improves β-cell function and insulin sensitivity often allowing the discontinuation of insulin therapy within a few months of initiation of the treatment." (PMID 29508275, 2018). "Multiple factors have been shown to modify the QoL in patients with DM2; the most prominent factors include the presence of diabetes distress, medication adherence, depression symptomatology, longer duration of diabetes, use of insulin, marital status, and comorbidities among others." (PMID 29764429, 2018). "Diabetes mellitus was present in 37 patients (38%) of which 14 patients were on insulin therapy." (PMID 29791495, 2018). "Our findings hence might provide novel insights into the molecular pathology of diabetes, which involves dysregulated insulin clearance from the liver, and hence may be a promising future therapeutic target for diabetes." (PMID 29415457, 2018). "Available experimental evidence indicates that insulin not only promotes peripheral nerve regeneration in vivo, but may prevent diabetes-induced functional deficits, too." (PMID 30364236, 2018). "Diabetes mellitus is a group of metabolic disorders caused either by the inability to produce insulin or by the body not being able to use insulin effectively or both." (PMID 30314443, 2018).
diabetes (continued). "Glucose-sensitive insulin release has attracted particular attention, since the development of insulin delivery systems for the self-regulation of blood glucose levels would be helpful for diabetes mellitus patients." (PMID 30961089, 2018). "The work addresses a binary question of whether having some extent of PN reimbursement helps alleviate the economic burden for patients who rely on PN-delivered insulin injections to manage their diabetes." (PMID 29699587, 2018). "In Brazil, the HAT study highlighted that hypoglycemic events are frequent among patients with insulin-treated diabetes and may compromise patient adherence to insulin treatment." (PMID 30479669, 2018). "The strict control of insulin plays an important role in preventing and treating diabetes." (PMID 30595798, 2018). "Case 2 had diabetes mellitus (MD) for 8 years, the insulin was used to control the blood glucose." (PMID 29995750, 2018). "The present study had the following 3 limitations: Considering the effects of oral hypoglycemic drugs or insulin therapy on blood glucose, patients who had a history of diabetes were excluded, which might affect the study results of blood glucose." (PMID 30313088, 2018). "Diabetes is categorized as either type I (insulin dependent) or type II (non-insulin dependent)." (PMID 29925761, 2018). "Among the older men, however, some of the variables representing risk factors for ED were not positively associated with pharmacy dispensing of ED medication, for example pharmacy dispensing of insulin or antidepressants and having received a diabetes diagnosis." (PMID 29101427, 2018). "Additionally, a maternal uncle had been diagnosed with diabetes at age 18 years and he was now on insulin but had been on oral hypoglycemic agents previously." (PMID 28766502, 2018). "Consequently, DPP-IV inhibition improves glucose tolerance in patients with diabetes by enhancing the insulin-producing effects of GLP-1." (PMID 30103438, 2018). "She had a history of diabetes for 10 years and was mainly treated with acarbose and insulin." (PMID 29954324, 2018). "Nevertheless, altered β-cell function and decreased β-cell mass may contribute to the defects in insulin release which is vital to the etiology of diabetes." (PMID 30532775, 2018). "In addition, we need to take into account that a significant proportion of patients with diabetes are treated with basal insulin on a permanent basis." (PMID 30373567, 2018). "Resting serum BDNF levels and diabetes risk factors, such as fasting glucose, insulin, homeostasis model assessment (HOMA-B—beta cell insulin secretory capacity) and (HOMA-IS—insulin sensitivity), and hemoglobin A1c (HbA1c), were measured after an overnight fast at baseline and 6 months." (PMID 30363954, 2018). "Diabetes alters the mitochondrial proteins in insulin-responsive tissues." (PMID 30266947, 2018). "Together with the destruction of pancreatic tissue in certain forms of the disease, reduced CFTR-stimulated insulin secretion might contribute to diabetes in some patients with cystic fibrosis." (PMID 29773801, 2018). "It has recently been proposed to re-define diabetes based on six clinical parameters [BMI, age at diagnosis, hemoglobin A1c, glutamate decarboxylase autoantibodies (GADAs) (evidence of autoimmunity); β-cell function and insulin sensitivity]." (PMID 30618774, 2018). "However, evidence is still lacking regarding the practical implementation of basal-bolus insulin regimen in long-term diabetes." (PMID 30918874, 2018). "Liver-derived cells can be transdifferentiated into insulin-producing cells through a process mediated by the ectopic expression of TFs, and the resulting cells could potentially be used to treat diabetes." (PMID 29768476, 2018).
diabetes (continued). "Type 2 diabetes mellitus (T2DM), a worldwide chronic disease accounting for more than 90% of all diabetic patients, is characterized by hyperglycemia due to a deficiency in insulin secretion, excessive hepatic glucose production and insulin resistance." (PMID 29783787, 2018). "In the development of diabetes, miRNAs have been reported to regulate metabolism, adipocyte differentiation, pancreatic development, β-cell mass, insulin biosynthesis, secretion, and signaling, underscoring their important role in the early diagnosis, pathogenesis and treatment of diabetes." (PMID 30093963, 2018). "MafA, an efficacious activator of insulin gene transcription, may be a novel target for the treatment of diabetes." (PMID 30337946, 2018). "However, in developed countries, the vast majority of persons diagnosed with T2D receive insulin or oral anti-diabetes medications, making it difficult to include such a group in clinical and postmortem studies." (PMID 30383799, 2018). "Changes in intestinal microbiota may influence the host's sensitivity to insulin with the onset of diabetes." (PMID 30539026, 2018). "In our sample of subjects without known diabetes, myonectin concentrations were positively associated with measures of IR like the iAUCins and negatively associated with insulin sensitivity measures like the ISI-Gutt." (PMID 29445355, 2018). "Decreased production of NO∙ may result in cellular dysfunction, decreased blood flow, glucose transport, insulin resistance, insulin secretion, hypertension, and diabetes." (PMID 30577559, 2018). "This study suggests that AX particles could be excellent candidates for the controlled release of insulin and probiotics in the colonic region as an alternative for the treatment of diabetes." (PMID 30186541, 2018). "Principally, this cognitive event could be explained by the insulin-resistant state observed in MS and diabetes." (PMID 30154946, 2018). "Interestingly, treatment of diabetes with exenatide is known to work well together with the pioglitazone and delays the need for insulin replacement." (PMID 29793507, 2018). "Diabetes mellitus presents from a constellation of heterogeneous malfunctions witnessed by episodes of hyperglycemia and glucose intolerance resulting from lack and/or defective insulin or insulin action." (PMID 29777127, 2018). "Our results do not support an association between HbA1c or insulin sensitivity and verbal memory in individuals with recent-onset diabetes." (PMID 30159333, 2018). "In South Korea, insulin levels are usually measured for established diabetics." (PMID 30474549, 2018). "It is also possible that a genetically determined insulin effect could lead to both failure to grow and diabetes." (PMID 29997576, 2018). "The strategies promoting insulin secretion have been the mainstay of the treatment of diabetes." (PMID 30301245, 2018). "Altogether, the data suggest an important and unexplored role of liver macrophages in the regulation of atherosclerosis and insulin sensitivity, a finding that has significant implications for diabetes, obesity and many other human diseases involving hyperlipidemia and insulin resistance." (PMID 30483256, 2018). "Several susceptibility loci for T1D have been found and diabetes-predictive circulating autoantibodies against beta cell antigens such as insulin can be found in non-diabetic subjects years before clinical manifestation of the disease." (PMID 30386256, 2018). "Considering the complexity of the physiological mechanisms of insulin resistance in diabetes and obesity related to metabolic flexibility in different tissues, crosstalk between muscle and adipose tissues needs to be established as both are essential components in this process." (PMID 30666216, 2018). "Most participants were taking tablets to manage their diabetes, but 10 (13%) were taking insulin." (PMID 29859061, 2018).